ALB (albumin)
Diseases named in the same sentence as ALB in open-access papers (continued):
Sharing a sentence is not in itself a finding about the gene and the disease.
COVID-19 (continued). "Thus, analysis of albumin concentrations requires caution, especially in people with COVID-19 who have been administered corticosteroids, which can further modify albumin concentrations." (PMID 32992538, 2020). "Answer: In a prospective cohort study of 701 patients with COVID-19, while serum albumin levels were significantly low in patients who died from COVID-19; blood urea nitrogen, serum creatinine, serum potassium, creatinine kinase, and lactate dehydrogenase levels were found to be significantly high." (PMID 32713282, 2020). "Considering that the therapeutic measures such as intravenous albumin infusion may mask the true serum albumin levels of patients with COVID-19, we selected the initial albumin on admission for analysis." (PMID 33110593, 2020). "Similar to the hepatic injuries associated with COVID-19, the most frequent GI clinical manifestations of SARS included elevations in levels of serum bilirubin, ALT and/or AST, and decreased levels of serum albumin." (PMID 32903492, 2020). "However, analyses of the NRI and IDI demonstrated that the PNI (which contains the albumin level and lymphocyte count) conferred additional performance for the prediction of critical illness due to COVID-19 as compared with that of albumin level alone." (PMID 33521032, 2020). "A similar study found a strong association between COVID-19 severity and elevated levels of C-reactive protein (CRP), procalcitonin, interleukin-6, neutrophils, hs-troponin T, lactate dehydrogenase (LDH), ferritin and D-dimers, along with decreased levels of albumin, lymphocytes and platelets." (PMID 40283188, 2025). "However, there was a significant difference in mean serum albumin values between the COVID-19 group and the H1N1 group of ARDS patients on mechanical ventilation, with values of 28.73 ± 4.97 vs 31.93 ± 4.85 (mean ± SD), resulting in a p-value of 0.05, as indicated by an independent t-test." (PMID 40017475, 2025). "where a decrease in albumin level was associated with increased mortality, in-hospital complications, and longer hospital and ICU stays, and improvement in overall in-hospital outcomes with albumin replacement therapy in ARDS and ARF related to COVID-19 and pneumonia." (PMID 40130722, 2025). "Albumin’s potential in drug delivery, wound healing, antioxidant therapy, and tissue engineering continues to expand, particularly in the context of critical illnesses such as COVID-19, where the albumin globulin ratio has been identified as a predictor of disease severity and mortality." (PMID 40699702, 2025). "Attending physicians should maintain a vigilant approach to recognize the potential extrapulmonary manifestations of COVID-19 patients in the ED, and serum albumin levels could help enhance situational awareness and rational resource allotment amidst the dynamically evolving COVID-19 situation." (PMID 38639116, 2024). "The combined changes of LPS and albumin could seriously influence thrombotic outcomes in COVID-19." (PMID 39456513, 2024). "However, there was another research found that both gross changes in albumin and myoglobin may early disclose COVID-19 fatal outcomes." (PMID 39164612, 2024). "The three groups had varied mean and standard deviation values for laboratory tests such PT, fibrinogen, D-dimer, LDH, total bilirubin, ferritin, AST, ALT, albumin, creatinine, and blood urea nitrogen, suggesting that COVID-19 may have had an impact on these measurements." (PMID 37376524, 2023). "Circulating suPAR levels positively correlated with COVID-19 severity, the need for O2 therapy, the total leukocytes count, and the neutrophils to lymphocyte ratio, while they were negatively correlated with the O2 saturation level, albumin, blood calcium, lymphocytic count, and GFR." (PMID 37108340, 2023). "The ALBI grade 3 and FIB-4 index ≥ 3.25, higher PT-INR, hsCRP levels and lower albumin levels could be associated with mortality in non-cirrhotic CLD patients with COVID-19." (PMID 38077441, 2023).
COVID-19 (continued). "The serum albumin concentrations were significantly decreased in the group of COVID-19 patients compared to healthy volunteers (p < 0.001), and as the disease progressed and the condition of COVID-19 patients worsened, HSA gradually decreased for both sexes (p < 0.001)." (PMID 36982882, 2023). "Based on the obtained CW-EPR data, we hypothesize that in COVID-19 patients, high levels of ROS are the cause of albumin oxidation, the formation of biologically non-functional end products, and the loss of antioxidant activity." (PMID 36982882, 2023). "Our results showed the existence of an inverse relationship between albumin and D-dimer levels, which indicates the existence of an inextricable link between inflammation and thrombosis, which is clinically manifested by a severe clinical picture and a possible fatal outcome in COVID-19." (PMID 37109161, 2023). "According to the literature, elevated urinary protein levels in AKI associated with COVID-19 are mostly a result of the presence of low molecular weight proteins (not albumin) that could be a sign of decreased reabsorption due to injured tubular function." (PMID 36127479, 2023). "Similarly, a urea/ALB ratio (UAR) ≥ 12.17 was observed to double the risk of ICU mortality in hospitalized COVID-19 patients, regardless of other inflammatory parameters." (PMID 37762957, 2023). "Moreover, there was high proportion of critically ill COVID-19 patients where it could be expected that albumin levels would correlate with worse disease progression." (PMID 35160039, 2022). "However, in our cohort, we observed lower antibody titers in PD patients compared with HD patients, which could be explained by a lower serum albumin level, a well-known risk factor for reduced HMI for COVID-19 and other vaccines in the PD group." (PMID 35891228, 2022). "Moreover, serum albumin levels have been shown to be prognostic marker in COVID-19 patients." (PMID 35601226, 2022). "Further, assessment of cerebrospinal fluid from COVID-19 patients presenting with neurological symptoms revealed elevated albumin levels, suggesting that impaired blood-brain barrier or blood-cerebrospinal fluid barrier properties may play a role during the COVID-19 disease course." (PMID 35242762, 2022). "Therefore, our results indicated that ALB concentration was a risk factor in viral shedding in patients with non-severe COVID-19." (PMID 36620263, 2022). "Derived laboratory biomarkers such as the de Ritis, CRP-to-albumin, LDH-to-hemoglobin, CRP-to-lymphocyte, and LDH-to-albumin ratios show significant association and discrimination with all-cause mortality in KTR with COVID-19, suggesting its potential risk stratification role." (PMID 36556433, 2022). "The substantial majority of studies focused on COVID-19-associated liver abnormalities evaluate peak levels of liver enzymes, such as aspartate aminotransferase (AST), alanine aminotransferase (ALT), alkaline phosphatase (ALP), gamma-glutamyl transferase (GGT), total bilirubin (TBIL) and albumin." (PMID 35956107, 2022). "In addition to nutritional risk scores, other nutritional markers have also been associated with adverse clinical outcomes among medical and COVID-19 patients, such as obesity and low albumin levels, which are both independently correlated with ICU admission and a more severe course of COVID-19." (PMID 36014955, 2022). "We suggest that oxidized albumin could be involved in COVID-19 pathophysiology." (PMID 36077496, 2022). "Serum albumin measurement may serve as a predictor of disease severity in patients with COVID-19." (PMID 36077496, 2022). "In addition, NEFA cytotoxicity may be further accentuated in obese patients with severe COVID-19 due to decreased albumin levels, contributing to more free fatty acids in serum because these are transported in the plasma by albumin." (PMID 35784579, 2022).
COVID-19 (continued). "Consistent with our findings, observational studies have reported a negative correlation between serum albumin and the risk of severe COVID-19, and elevated direct bilirubin could predict worse prognostics of COVID-19." (PMID 34122505, 2021). "Likewise, the combination of the neutrophil count with serum albumin values improves the area under the receiver operating characteristic (ROC) curve for predicting mortality in COVID-19 patients compared to those found when the neutrophil count or serum albumin are used separately." (PMID 34683480, 2021). "Blood parameters, such as hemoglobin and albumin levels, may allow for a direct correlation between COVID-19 progression and heme availability, since they are inevitably connected to the processing of hemoglobin and heme, respectively, under hemolytic conditions." (PMID 33925394, 2021). "Therefore, early treatment with human albumin in severe cases of COVID-19 patients before the drop in albumin levels might have positive outcomes and needs to be further investigated." (PMID 35098205, 2021). "Third, the frequent serum albumin decrease in hospitalized COVID-19 patients should be interpreted cautiously because patients with other diseases requiring prolonged hospitalization may also show this result, and the absence of a control group may hinder a valid conclusion." (PMID 34399709, 2021). "Thus, we believe it is crucial to understand the possible mechanisms by which some pathophysiological elements of COVID-19 may down-regulate serum albumin levels." (PMID 34683480, 2021). "Moreover, albumin levels were significantly decreased in COVID-19 patients (p = 0.02)." (PMID 34680053, 2021). "Since the combined use of the IL-15-to-albumin ratio acts as an accurate mortality predictor, we believe that it is of great importance to discuss the possible mechanisms through which these molecules may contribute to the progression and severity of COVID-19." (PMID 34683480, 2021). "Although albumin decreased remarkably in both COVID-19 and CAP groups, there was still a significant difference between the two groups; the decrease in the CAP group was more obvious than that in the COVID-19 group, which could contribute to the differentiation of COVID-19 from CAP." (PMID 33534722, 2021). "Therefore, bismuth-based drugs but also zinc-chelating agents (and exogenous albumin) might be potentially effective against COVID-19." (PMID 33673459, 2021). "Additionally, albumin levels lower than 29.6 g/L could independently predict mortality in COVID-19 patients admitted to the ICU." (PMID 33803339, 2021). "Viewed altogether, the findings from this exploratory clinical study suggest that early monitoring of two key predictors of lung abnormalities, namely, circulating levels of CRP and albumin, may permit early therapeutic interventions to avoid or limit COVID-19 progression." (PMID 33396578, 2020). "Furthermore, they found that these COVID-19 patients had lower levels of lymphocyte and serum albumin, higher levels of lactate dehydrogenase, B-type natriuretic peptide, and D-dimer, which might be correlated with severity of illness." (PMID 33344469, 2020). "We performed Cox regression analysis, which demonstrated that comorbidity (HR 3.17, 95% CI 1.96–5.11), ALB level (HR 3.67, 95% CI 1.91–7.02), CRP level (HR 3.16, 95% CI 1.68–5.96), and age ≥60 years (HR 2.31, 95% CI 1.43–3.73) were independent risk factors for severe COVID-19 in these patients." (PMID 33330318, 2020). "Therefore, we compared the serum liver chemistries such as hepatic transaminases, total bilirubin, albumin, and prothrombin time to evaluate whether they can predict severity and mortality in COVID-19." (PMID 32793616, 2020). "Thus, it appears that inflammatory responses might be responsible for low serum albumin levels in COVID-19 patients with pneumonia." (PMID 33260480, 2020).
COVID-19 (continued). "Our results indicated that COVID-19 patients with elevated ALT or decreased ALP tended to be younger, while patients with elevated AST or reduced albumin tended to be older." (PMID 41574293, 2025). "Our group has developed the ALKA score, a simple tool to predict COVID-19 complications, using four variables: age, lactate dehydrogenase (LDH), kidney function, and albumin." (PMID 40901500, 2025). "The role of lactate and albumin and their impact on in-hospital outcomes in ARDS, Pneumonia, and ARF due to COVID-19 have been explored in different studies." (PMID 40130722, 2025). "The results showed that the intensities of most of these metabolites—except albumin, L-HDL-CE, and L-HDL-C—were higher in the COVID-19 group compared to the Other-D group." (PMID 40399692, 2025). "COVID-19 patients also showed higher ferritin, CRP, and urea, and lower platelet and albumin levels (p < 0.001)." (PMID 41286678, 2025). "Classical inflammatory biomarkers, C-reactive protein (CRP), albumin, and red blood cell distribution width (RDW) have previously been reported to be prognostic in hospitalized COVID-19 patients." (PMID 40431641, 2025). "CRP, albumin, and RDW have also been shown to be deranged and predictive of outcomes in severely ill COVID-19 patients." (PMID 40431641, 2025). "Key variables assessed included the albumin/creatinine ratio, age, serum albumin levels, CRP, and history of COVID-19." (PMID 41170570, 2025). "Conversely, patients with both COVID-19 and CDI had lower albumin levels (29.9 g/L ± 5.3) compared to the COVID-only group (33.6 g/L ± 5.5, p < 0.001), suggesting poorer nutritional status or greater disease severity." (PMID 39857810, 2025). "In this cohort study of hospitalized patients with COVID-19, elevated levels of the kidney biomarkers CysC and NGAL along with lower albumin concentrations were significantly different between patients who were discharged and those who died." (PMID 40649865, 2025). "Compared with controls, COVID-19 patients had markedly higher serum asprosin, ferritin, CRP, and urea levels, while platelet counts and albumin were significantly lower (all p < 0.001)." (PMID 41286678, 2025). "Additionally, our findings indicate that COVID-19 may lead to a decrease in albumin levels." (PMID 38549094, 2024). "The lymphocyte count, C-reactive protein, lactate dehydrogenase, D-dimer, albumin and DAR were likely to influence the capacity to predict adverse outcomes of COVID-19 patients." (PMID 39144651, 2024). "In this study, we found that vitamin D deficiency resulting from low total 25(OH)D and VDBP levels, as well as low calcium and albumin levels, was more common in adult patients hospitalized in the ICU due to COVID-19." (PMID 39272727, 2024). "We observed lower levels of ALB, APOM, and TF in patients with COVID-19 (and more so in patients with COVID-19 who were admitted to the ICU) relative to patients without COVID-19." (PMID 39027641, 2024). "We analyzed correlations between neopterin levels, CRP, albumin levels, and the CRP/albumin ratio in severe COVID-19 patients." (PMID 39058886, 2024). "Patients treated at the ICU were more likely to have cardiovascular and respiratory symptoms, as well as a history of symptomatic COVID-19, higher CRP, PCT, BNP and lower albumin levels." (PMID 39596959, 2024). "Baseline levels of sNOX2-dp, LPS, zonulin, D-dimer, albumin, and hs-CRP were significantly higher in COVID-19 compared to controls." (PMID 39456513, 2024). "Patients treated at the ICU were more likely to have cardiovascular and respiratory symptoms, as well as a history of symptomatic COVID-19, higher C-reactive protein (CRP), PCT, BNP and lower albumin levels." (PMID 39596959, 2024). "Significant differences were found in baseline levels of D-dimer, albumin, and hs-CRP between controls and COVID-19 patients." (PMID 39456513, 2024).
COVID-19 (continued). "Severe COVID-19 cases, similarly to our findings, show raised AST, ALT, and GGT levels with reduced albumin, although mean albumin remained normal in different studies." (PMID 38398462, 2024). "The BUN to albumin ratio reflects both kidney function (BUN) and nutritional status (albumin), both of which are important factors in the COVID-19 prognosis." (PMID 38074058, 2023). "The multivariate analysis revealed the most significant risk factors for hyponatremia in COVID-19 were increasing age, COVID-19 symptoms, ANC, ALC, NLR and serum albumin having p-values of 0.006, 0.004, 0.001, 0.001, 0.023 and 0.004 respectively." (PMID 36694746, 2023). "Most patients with COVID-19 complicated with liver injury showed mildly elevated transaminases, and some patients had elevated GGT, ALP, and total bilirubin, and decreased ALB." (PMID 36860673, 2023). "Mapping relation examination between COVID-19 and Ephedra-Glycyrrhiza exhibited that the key markers were tumor necrosis factor-α (TNF-α), interleukin-2 (IL-2), albumin (ALB), FOS proto-oncogene, and prostaglandin- endoperoxide synthase 2 (PTGS2)." (PMID 37654998, 2023). "Using creatinine, albumin, CRP, white blood cell count and clinical characteristics five phenotypes of hospitalized COVID-19 patients were identified." (PMID 37507773, 2023). "Measurement of plasma [free Trp] along with albumin and NEFA will therefore be an important requirement in future studies of COVID-19 pathophysiology." (PMID 37486805, 2023). "For severe COVID-19, TBIL, CRP/ALB, albumin, neutrophil percentage, lymphocyte percentage, ALC, and AEC are also important biomarkers." (PMID 37448393, 2023). "Data of albumin levels (g/dL) and double-integrated EPR spectra (a.u.)in COVID-19 patients and healthy volunteers." (PMID 36982882, 2023). "At the same time, COVID-19-induced liver damage leads to an increase in liver enzymes such as AST, ALT, and ALP, and a decrease in circulating levels of albumin." (PMID 37873785, 2023). "New risk factors for an increased sFlt1/PlGF ratio include lower blood IgG, albumin, C4 levels, and larger sFLC, HS-CRP, B2-M, TPR, phthalate, COVID-19, AFLP, peripartum cardiomyopathy, and aberrant myocardial performance and OSI." (PMID 37047717, 2023). "The network map and PCA plot showed that the closest neighbors of COVID-19 severity were ferritin and age, and CRP, scoring index of chest x-ray, albumin, and LDH were the next closest neighbors of these 3 factors." (PMID 36668902, 2023). "The deterioration model of COVID-19 was constructed with five indices, including C-reactive protein, neutrophil count/lymphocyte count (NLR), albumin/globulin ratio (A/G), international normalized ratio (INR), and blood urea nitrogen (BUN)." (PMID 37122321, 2023). "Individuals infected with neurological sequelae of COVID-19 have shown signs of BBB dysfunction and endotheliopathy including elevated albumin, protein, and immunoglobulin index in CSF." (PMID 37427212, 2023). "Biologically, ALB has been shown to exert a down-regulating effect on the production of angiotensin converting enzyme 2 (ACE2), which is the target receptor for COVID-19." (PMID 37762957, 2023). "Previous studies showed that severe COVID-19 patients had more comorbidities, higher levels of LDH, D-dimer, CRP, leukocytes, and neutrophils, as well as lower levels of albumin, platelet, and lymphocyte counts." (PMID 38027038, 2023). "LDH levels in patients with COVID-19 correlated significantly with CRP (ρ = 0.31, p = 0.024), albumin (ρ = -0.40, p = 0.002), CKMB_M (ρ = 0.31, p = 0.028), and myoglobin (ρ = 0.29, p = 0.036)." (PMID 37965268, 2023). "The odds ratio (OR) values of IgG type, platelet, albumin, and lymphocyte were <1, respectively, and the OR values of age, C-reactive protein (CRP), COVID-19 IgM, and comorbidities were >1, respectively." (PMID 36081775, 2022).